CD44 (CD44 molecule (IN blood group))
Diseases named in the same sentence as CD44 in open-access papers (continued):
Sharing a sentence is not in itself a finding about the gene and the disease.
cancer (continued). "Taken together, these results suggest that CD44-positive cancer cells expressing Oct4 are induced by cisplatin, which may contribute to drug resistance." (PMID 27244887, 2017). "Higher levels of CD44 expression was reported to be significantly correlated with malignant clinicopathological characteristics and worse prognosis of patients in multiple types of cancers." (PMID 28262804, 2017). "MiR-520b was significantly down-regulated in all cancer cell lines, whereas CD44 was up-regulated." (PMID 28515423, 2017). "EGFR can activate cancer cell motility and invasion by regulating CD44 and EMMPRIN." (PMID 28465354, 2017). "Overwhelming evidence up to now supports CD44 could be used as a surface marker for isolating CSCs from breast, prostate, pancreas and other human cancers." (PMID 28076853, 2017). "To elucidate the molecular basis whereby MSI-2 promotes the malignant behaviors of CC cells, we examined the mRNA expression of several metastasis-related genes (SNAIL, Vimentin and E-cadherin) and cancer stem cell marker CD44 in MSI-2 overexpression cells or knockdown cells." (PMID 29073938, 2017). "We also investigated whether autophagic and PPARγ-mediated pathways could modify a phenotype aspect linked to cancer stem cells (CSCs) population, measured by CD24/CD44 differential expression." (PMID 28932171, 2017). "ALDH-1, CD133, CD44, Lgr-5, and Msi-1 are markers for the acquisition of cancer stemness." (PMID 28862656, 2017). "ALDH and CD44 are stem cell markers commonly used to identify cancer stem cells." (PMID 28624784, 2017). "Several splicing factors have been shown to enhance splicing of the CD44 variable exons in cancer, such as SAM68, RBM3 and ESRP1, suggesting that regulation of their expression or activity may underlie CD44 splicing control in CSCs." (PMID 28137272, 2017). "CD44 protein exhibits high expression on the cell membranes of mouse cancer 4T1E/M3 cells." (PMID 28230204, 2017). "Consequently, we observed that cancer cells that reside in a CD44+/CD24− state are characterized by increased accumulation of DNA copy number alterations, greater genetic diversity and improved adaptability to drug treatment." (PMID 28092266, 2017). "This indicated that HA-coated CS NPs effectively promoted drug accumulation in those cancer cells where CD44 was highly expressed on the cell surface; specific binding between HA and CD44 might facilitate the uptake of HA-coated CS NPs." (PMID 28068992, 2017). "RHAMM is a cytoplasmic protein that is unconventionally exported to the cell surface during wound repair, where it binds with HA and activates CD44 resulting in stimulation of the Ras/Erk1,2 pathway, a cascade that functions in cellular proliferation and that often dysregulated in cancer." (PMID 29137675, 2017). "Furthermore, a compendium of TNBC cancer stem cell markers such as CD44, ABCG2 transporter and aldehyde dehydrogenase (ALDH1) were greatly downregulated in the MDA-MB-231 cells with DANCR knockdown." (PMID 28760736, 2017). "Furthermore, the interaction of HA with its binding partners, the hyaladherins, such as CD44, is essential for sustaining tissue integrity and is likewise related to cancer." (PMID 29062810, 2017). "In fact, CD44 is proposed to be one of the important surface markers for cancer stem cells." (PMID 28837080, 2017). "In line with this hypothesis, the EMT-TF ZEB1, which is upregulated in several human cancers, directly inhibits ESRP1 expression, thus causing AS changes in the CD44 gene." (PMID 28137272, 2017). "CD44 gene has been shown to play a significant role in the EMT phenotype in various cancers." (PMID 28279210, 2017). "Furthermore, the expression of cancer stem cell (CSC) markers CD44, CD133, Nanog and Sox2 were detected in neoplastic samples of these patients by immunohistochemistry." (PMID 28262804, 2017).
cancer (continued). "Consistently, ALDH1 and CD44 cancer-stem markers were also reduced by miR205, as well as TAZ, which is involved in the cancer-stem cells renewal and mammospheres formation, and E2A.E12 that maintains the mesenchymal characteristics of this cellular subpopulation." (PMID 29182685, 2017). "Our results showed that EGF induces EMT process in OSCC cells, which correlates with the acquisition of cancer stem-like properties, including the enrichment of CD44+/CD24− population of cancer cells and an increased expression of CSC-related genes, aldehyde dehydrogenase-1 (ALDH1) and Bmi-1." (PMID 27926487, 2017). "A mesenchymal phenotype, characterised by low expression of E-cadherin (CDH1), high expression of vimentin (VIM) and high expression of EMT-inducing transcription factors, such as TWIST1, ZEB1, SNAI1 and SNAI2 moreover correlates with the expression of cancer stem cell markers CD44 and CD90." (PMID 29299154, 2017). "How STAT3 confers HICR also may be related to its ability to upregulate CD44, a marker of cancer stemness." (PMID 29036915, 2017). "During the past decades, the role of CD44 in cancer development has been revealed and valued." (PMID 28659634, 2017). "It was observed that ACEA decreased CD44+/CD24-/low/ESA+ cancer stem cell invasiveness." (PMID 29552056, 2017). "Importantly, we show that miR205 inhibited SUM159PT cancer-stem cell renewal, expression in mammospheres of CD44 and ALDH1 stem-cell markers, TAZ, and E2A.E12." (PMID 29182685, 2017). "Notably, the expression of a cancer stem cell marker, CD44, was correlated with T stage, high Fuhrman grade and metastasis in ccRCC." (PMID 28846080, 2017). "Thus, CD44 seems to be involved in the processes of contact inhibition in normal cells as well as the anchorage-independent growth of cancer cells." (PMID 29062810, 2017). "Thus, multicellular cancer groups in ILCs lack adherens junctions but retain CD44 between juxtaposed neighbor cells." (PMID 28894989, 2017). "CD44 and CD44 s mediated adhesion to hyaluronan might partially be responsible for augmented cancer cell adhesion during post-operative inflammatory conditions." (PMID 27074785, 2016). "CD44 is expressed on malignant cells, as well as on cancer stem cells." (PMID 27454254, 2016). "CD44 protein was initially identified as the receptor for hyaluronic acid (HA), and involved in proliferation, differentiation and motility of both normal and cancer cells." (PMID 27323782, 2016). "Importantly, it is a novel finding in our study that CD44 is an upstream positive regulator of Oct4, which is an regulater of stemness and promotes cancer cells proliferation and metastasis." (PMID 26769843, 2016). "CD133, CD44 and Oct4 are commonly used as cell membrane biomarkers to identify cancer stem cell." (PMID 27145365, 2016). "Taken together, these results indicate that sE-selectin may have biological function via CD44 in a broad range of circulating cells including leukocytes and cancer cells." (PMID 27220365, 2016). "The CD133+/CD44+ population, which comprises the cancer initiating cells (CICs), may be the best biomarker for the early detection of CRC." (PMID 27738333, 2016). "Furthermore, we found BMP4 to potently inhibit tumorsphere formation and to reduce the CD44+/CD24− cancer stem cell population in TNBC cells." (PMID 27759034, 2016). "These bioinert, biodegradable, and biocompatible polysaccharides conjugate with drugs or constitute polymeric nanocomplexes/nanoparticles to deliver hydrophobic anticancer drugs or small interfering RNA (siRNA) to target cancer cells, which overexpress CD44 and isoforms." (PMID 28029125, 2016). "Collectively, CD44 could be a gatekeeper of the cancer stem cells and might be a core regulator of stemness, which can modulate the expression of some important stem cell markers and is co-expressed with others." (PMID 26769843, 2016).
cancer (continued). "Moreover, using SAGE-Seq libraries, we identified 2314 genes differentially expressed in CD44+ cancer cells compared to CD44+ normal breast epithelium cells." (PMID 26673618, 2016). "Interestingly, some cancer stem cell (CSC) associated transcripts, such as CD117, CD34, Oct-4, CD44, ALDHA2 and Nanog, were down regulated in the A549 and PG cells expressing miR-708-5p." (PMID 26678031, 2016). "Similarly, cancer stem-like spheres induced from de-differentiated HCC-derived cell lines showed increased expression of stemness markers, such as CD44, and possessed resistance to anti-cancer drugs." (PMID 26985909, 2016). "Human cancer stem-like cells (CSCs)/cancer-initiating cells (CICs) can be isolated as side population (SP) cells, aldehyde dehydrogenase high (ALDHhigh) cells or cell surface marker-positive cells including CD44+ cells and CD133+ cells." (PMID 27415781, 2016). "CD44 is a compelling marker for cancer stem cells of many solid malignancies." (PMID 27200096, 2016). "Many malignant tumors express high levels of CD44, thus, CD44 may be used as an indicator of aggressive behavior of some human malignancy." (PMID 26821610, 2016). "CD44 showed to be expressed by neoplastic cells in MEC like other type of cancer." (PMID 26821610, 2016). "Increasing evidence indicates that CD44 has a role in cancer." (PMID 28000766, 2016). "Further, effectiveness of bLf-Dox conjugates against drug resistant CD44+/EpCAM+ double positive cancer stem cell enriched DU145 cells was tested, which showed that both Apo-bLf-Dox and Fe-bLf-Dox were capable of inhibiting clonogenic, migration as well as 3D growth properties of these cells." (PMID 27576789, 2016). "Biological evaluation of nanoparticles was done in CD44+ cancer cells." (PMID 27473554, 2016). "Compared to parental MCF7 cells, MCF7/C6 cells are aggressive with increased capacity of invasiveness and migration, and inhibition of CD44 expression could effectively reduce cancer cell invasiveness and migration in MCF7/C6 cells." (PMID 27036550, 2016). "CD44 isoforms were also found to be deregulated as observed in many types of cancer." (PMID 27542596, 2016). "Higher CD44 expression is found in cancer stem cell population and confers chemoresistance." (PMID 27655682, 2016). "Therefore, we also isolated CD44+CD133+ cell fraction from established human CRC cell line SW480 for parallel tests (to the primary cancer cell line P6C)." (PMID 27302922, 2016). "After isolation of cancer cells from cytology-confirmed malignant pleural effusion by use of density gradient centrifugation, viable CD44+ cells clustering as spheres were observed and could be maintained in spheroid culture." (PMID 27306323, 2016). "Furthermore, both CD44 and RHAMM are associated with the development of stem cell and cancer stem cell." (PMID 27999774, 2016). "Furthermore, the MtDP PC3 cells were resistant to therapeutic treatments and contained greater cancer stem cell-like subpopulations: CD44+, ABCG2+, side-population and ALDHbright." (PMID 27248169, 2016). "Recent studies suggested that CD44 is a cancer stem cell marker." (PMID 27505250, 2016). "BORIS-positive cells expressed cancer stem genes including CD44, ALDH1, NANOG, OCT4 and SOX2." (PMID 26849232, 2016). "Additionally, CD44 is an important stem cell marker for multiple solid tumors, which leads to the development and progression of cancer." (PMID 26974151, 2016). "Furthermore, mDia1-deficient cells cultured in 3D matrix showed impaired expression of the cancer stem cell marker genes, CD44 and CD133." (PMID 26893363, 2016). "CD44, a transmembrane receptor reported to be involved in various cellular functions, is overexpressed in several cancer types and supposed to be involved in the initiation, progression and prognosis of these cancers." (PMID 27463372, 2016).
cancer (continued). "Their results suggested that combined expression of embryonic stem cell markers EZH2 and SOX2 might be used to identify potential cancer stem cells as a minor (<10%) subgroup in CD44+ prostatic adenocarcinoma cells." (PMID 27447616, 2016). "Furthermore, holospheres contained higher numbers of head and neck CSCs, as detected by the CD44 cancer stem cell marker and aldehyde dehydrogenase (ALDH) enzymatic activity." (PMID 26742076, 2016). "We investigated whether PIM mRNA expression correlated with expression of a cancer stem cell marker CD44." (PMID 27120806, 2016). "In this study, we provide novel evidence to the ability of the TME to regulate intra-tumoral heterogeneity in Luminal-A tumors and to enrich the cancer cells with two sub-populations: CD44+/CD24low/− cells with a stem-like phenotype and CD44+/β1+ cells that express high levels of adhesion molecules." (PMID 27835603, 2016). "It is believed that CD44 and Oct4 were expressed in most of benign and malignant prostate cells, which is not likely to be representative for a very small proportion of cancer cells (such as cancer stem cells)." (PMID 27447616, 2016). "Compared to parental cancer cells, spheroid cells overexpressed CD44, CD133, Oct4, Nanog, β-catenin, SOX2, Gli1 and p-ERK, which provided evidence for the existence of CSCs and suggested some of these markers might be used to identify gastric CSCs." (PMID 26769843, 2016). "Our data also showed that inhibition of CD44 expression could effectively reduce cancer cell invasiveness and migration in MCF7/C6 cells." (PMID 27036550, 2016). "HA is reported to possess strong affinity toward the CD44 overexpressing cancer cells." (PMID 27835895, 2016). "Similarly, integrin β1 has been shown to block apoptosis induced by cisplatin via ERK and MAP kinase and CD44 molecule has been show to promote PI-3 kinase-mediated oncogenic signaling and cisplatin resistance in cancer cells." (PMID 27835877, 2016). "We hypothesized using HA as carrier and targeting moiety simultaneously may reverse the multiple drug resistance of cancer stem cells via affecting CD44 and regarding physical correlation of P-gp and these markers." (PMID 27473554, 2016). "In our study, we synthesized CD44-PEG-GNCs that exhibit promising effects for cancer therapy." (PMID 27255899, 2016). "CD44 was considered as a marker of cancer stem cells from many organs including prostate." (PMID 27447616, 2016). "Moreover, the CD44 protein has been identified as a biomarker of side population cells or cancer stem-like cells in the gastric cell lines MKN-45, MKN-74, NCI-N87, and BGC-823." (PMID 26839535, 2016). "Cancer stem cells (CSCs) have been identified and isolated from acute myeloid leukemia and various solid tumor types based on the expression of putative surface markers, such as CD44 and CD133." (PMID 27302922, 2016). "Furthermore, the GNCs underwent bio-conjugation to anti-CD44 monoclonal antibodies to enhance their targeting of cancer cells." (PMID 27255899, 2016). "Emerging evidences have indicated that CD44 is a poorer prognostic indicator in several carcinomas." (PMID 27521216, 2016). "Although the nature of CSCs is still the subject of debate, CD44+ human carcinomas are highly malignant and resistant to therapy, and the presence of CD44 has been shown to confer increased metastatic potential, properties that are frequently associated with CSCs." (PMID 27293448, 2016). "This would explain the lower expression of the CD44 in low-grade cancers in our series." (PMID 25129125, 2015). "Chemotherapy induces cancer cell apoptosis; our previous research indicated that chemotherapy-induced apoptosis may activate cancer stem-like cells (CD44+/CD24−) in MCF-7 and that upregulation of MUC1 occurred." (PMID 26016502, 2015).
cancer (continued). "Depletion of CD44 positive stem cancer cells in the presence of VTD suggests this alkaloid may target a sub-population of cancer stem cells through the UBXN2A-mot-2 pathway as described for other natural products." (PMID 26188124, 2015). "In conclusion, CD44 is the most prevalent cell surface marker of cancer stem cells (CSCs)." (PMID 26448753, 2015). "Prince el al. first described CSCs in H&N cancer as a subpopulation of CD44+/CD24−/low cells." (PMID 25428916, 2015). "This reflects both the complexity of CD44 regulation in cancers, and its tissue specificity." (PMID 25129125, 2015). "A lowering in LRP1 expression as observed in certain cancers (see supra) could thus result in CD44 accumulation at the cell surface and enforced cancer cell attachment." (PMID 26617523, 2015). "Different expression of the CD44 in endometrioid and papillary-serous type may reflect different pathogenesis of these types of cancer." (PMID 25129125, 2015). "This was first established in a study of pancreatic cancer that found specific splice variants of CD44 in metastasized cancer cells that were not present in the primary tumor cells." (PMID 25852822, 2015). "CD44 has lately emerged in CSC or cancer initiating cell studies as a biomarker." (PMID 25954275, 2015). "We found that OCT4 was expressed in CD44-positive cancer cells in NPCs." (PMID 26202311, 2015). "Additionally, high levels of CD44 and low levels of CD24 have been linked to chemotherapy resistance and cancer relapse in metastatic breast cancer." (PMID 25852822, 2015). "Initial trials with drugs conjugated to CD44 antibodies are complicated by various toxicities, which are partly due to the fact that anti-cancer drugs conjugated to a CD44 antibody may induce toxicity in both cancer and normal cells." (PMID 25909172, 2015). "Furthermore, we demonstrated that CD44-positive cancer cells can renew themselves or maintain their phenotypes when they are implanted in nude mice." (PMID 26202311, 2015). "Furthermore, these results support the existence of a newly uncovered mechanism by which CD44 increases drug resistance in cancer cells." (PMID 26299618, 2015). "Taken together, CD44 figures prominently in the MDR of cancer cells and CSCs via HA binding." (PMID 26322272, 2015). "In summary, targeting of CD44 by siRNAs or antibodies for therapy and the use of HA-coated nanoparticles or of anti-CD44 antibody conjugates for the delivery of therapeutic agents have been examined as attractive strategies in the treatment of cancer and chronic diseases." (PMID 25954275, 2015). "CD44 is used in other cancers as an efficient therapeutic target." (PMID 25797268, 2015). "The 4-hour time point also appears to be the optimum duration for the separation and enrichment of the breast CSCs (as denoted by the phenotype of CD44+CD24−/lowESA+) from the heterogeneous MCF7 cancer cells and the primary cells under static culture conditions." (PMID 25905435, 2015). "Thus, the regulation and manipulation of hyaluronan–CD44 interactions through lipid rafts have potential applications for the prevention of inflammatory disorders and cancer." (PMID 26347743, 2015). "In our microarray data, genes encoding cancer stem cell markers, such as CD44 and CD133, were not significantly upregulated." (PMID 25674539, 2015). "The modulation of CD44’s partition to lipid rafts may also offer potential avenues in inflammation and cancer therapy." (PMID 26347743, 2015). "Previous findings that CD44 can activate ERK and AKT and attenuate Hippo signaling collectively suggest that CD44 may function as a common upstream regulator of these three pathways to favor cellular avoidance of contact inhibition in cancer cells." (PMID 25605020, 2015). "Thus, various strategies are evolving for treatments of cancer that focus on HA and CD44, including interference with the HA-CD44v signaling, by either targeting drugs to CD44v, targeting drugs to the HA matrix, or interfering with HA-CD44v interactions." (PMID 26448753, 2015).